TNF (tumor necrosis factor)
Diseases named in the same sentence as TNF in open-access papers (continued):
Sharing a sentence is not in itself a finding about the gene and the disease.
tumor (continued). "A major activator of NF-κB is the cytokine tumor necrosis factor (TNF), which is mainly produced by activated immune cells, especially macrophages and T cells, but can also be expressed by tumor cells." (PMID 24098720, 2013). "There are many cytokines secreted by aHSCs that are associated with tumor invasion and metastasis, ingcluding HGF, EGF, IL-1, IL-2, IL-6, MMP-2, MMP-9, TGF-β, TNF-α, VEGF and Wnt families." (PMID 23622143, 2013). "The differentiation of naïve T cells into mature CD8 Teff or CD4 Th1 or Th17 cells is required for T cells to make full use of their functional attributes directed against tumor cells, such as cytotoxicity and production of IFNγ and TNFα." (PMID 24265631, 2013). "It was reported that MCP-1 favors tumor angiogenesis and early tumor growth by inducing TNFα, IL-1α, and VEGF by TAMs." (PMID 24377047, 2013). "The question of the effect of anti-TNF-α in skin carcinogenesis is, thus, especially relevant in view of the increased use of these drugs for the treatment of autoinflammatory immune diseases." (PMID 23533798, 2013). "Tumor necrosis factor-alpha (TNF-α) and interleukin-1 alpha (IL-1α) are produced by macrophages, and they play an important role in tumor conditions." (PMID 24959547, 2013). "TNFα is a cytokine secreted by activated macrophages and is an important component of the anti-tumor activity of macrophages." (PMID 23691064, 2013). "In response to inflammatory stimulation, macrophage or monocyte secretes TNFα that can induce apoptotic or necrotic cell death of certain tumor cell lines." (PMID 23819063, 2013). "When macrophages become activated, they release inflammatory mediators, such as nitric oxide (NO) and tumor necrosis factor (TNF-α) and interleukin (IL-6) to inhibit tumor formation and microbial infections." (PMID 23765218, 2013). "TNF is a major mediator of cancer-related inflammation and promotes tumor progression/metastasis through regulation of cytokines, adhesion molecules, metalloproteinases, and proangiogenic activities." (PMID 24350291, 2013). "IL1α/β and TNFα secreted by the tumor cells are common paracrine activators of CAFs induced inflammation in a variety of cancers and experimental models." (PMID 23630584, 2013). "These include treatment with tumor necrosis factor-alpha (TNF-α), inhibition of TGFβ-signaling, pretreatment with radiotherapy, and induction of hypothermia in the tumor." (PMID 24009717, 2013). "IFN-γ and TNF-α were significantly increased in the tumor tissues, suggesting a type I inflammatory response associated with the development of SCC frequently observed in gastrointestinal cancers." (PMID 23408900, 2013). "The malignancy produces a large amount of tumor necrosis factor (TNF) which promotes a proinflammatory tumor microenvironment." (PMID 23800251, 2013). "Regarding the importance of TNFα in various diseases including cancer, therapeutic approaches to target TNFα have been applied, although agents recently developed have shown some side effects including tumor promotion." (PMID 23818931, 2013). "This is well illustrated by recent data showing that TNF-mediated activation of NF-kB is stimulated by mcroglia-macrophages in the tumor microenvironment and lost in vitro, thus favoring a proneural phenotype in GBM NS." (PMID 24330732, 2013). "The tumor cells were stimulated for three days by TNFα + Estrogen + EGF in vitro then washed to remove the stimulators and inoculated to the mammary fat pad of mice." (PMID 24369447, 2013). "Whereas TNF-α can fully induce anti-tumor immune response and inhibit tumor formation and metastasis." (PMID 23593411, 2013). "On the whole, reduction of the cytokine TNF-α is bound to ameliorate some hallmarks of this tumour, such as cachexia." (PMID 23408945, 2013). "These lipid components decrease free proinflammatory cytokines such as tumour necrosis factor-α (TNF-α) which consequently reduces tissue damage, infiltration of macrophages and neutrophils, and attenuates tumour formation." (PMID 23401687, 2013).
tumor (continued). "An alternative strategy to avoid TNF-induced systemic toxicity is indeed to selectively target minute amounts of the cytokine to the tumor vessels." (PMID 24062984, 2013). "Since tumour development is characterized by an intense inflammatory reaction, TNF-α levels in the liver and tumour homogenates were measured as an inflammation marker." (PMID 23408945, 2013). "Since these IMiDs can enhance the functions of T cells and NK cells, suppress angiogenesis, inhibit TNF-α production, and directly repress tumor cell growth, they are potentially beneficial in treating cancer." (PMID 24391651, 2013). "This was accompanied by decreased levels of IL-6 and TGF-β, increased numbers of IFN-γ and TNF-α producing CD4+ T cells as well as a significant reduction of tumor growth." (PMID 22855687, 2012). "We also analyzed the effect of cryptopleurine on the TNF-α-induced expression of cyclinD1 and COX-2, both of which are associated with tumor cells proliferation." (PMID 22768286, 2012). "TNF is one of the pro-inflammatory cytokines that is constitutively present in tumor microenvoirnments and regulates various steps of tumorigenesis." (PMID 23152791, 2012). "NF-κB activation in inflammatory cells controls the production of pro-inflammatory cytokines, including TNFα, IL-1, IL-6, and IL-23, which mediate tumor promotion and progression, as well as NF-κB activation in tumor cells." (PMID 23284890, 2012). "These were increases of (systemic) levels of tumor-derived protein Hsp72 (heat shock protein), and of inflammatory cytokines IL-6 and TNF-α." (PMID 23233905, 2012). "TNF−/− mice had a lower incidence of total tumours, and where these did develop, there was a delay in onset as compared to those in wild-type mice." (PMID 23326670, 2012). "One of the mechanisms responsible for the specific killing of tumor cells by macrophages is the production of the cytokine tumor necrosis factor-alpha (TNF-α)." (PMID 22973555, 2012). "TNF-α is one of the most potent anti-tumor factors when used at high concentrations, but its systematic toxicity hampers its clinical applications." (PMID 23033967, 2012). "For example, radiation therapy (RT) particularly when localized to the tumor mass, given alone or in combination with immunostimulatory cytokines (IL-2 and TNFα) enhances its efficacy by generating anti-tumor specific CTL responses." (PMID 22849661, 2012). "Subsequently, the expression of TNF-related apoptosis-inducing ligand (TRAIL/Apo2L) and Fas/CD95 ligand (FasL) was stimulated on infiltrated immune cells and Fas expression on tumor cells, resulting in tumor necrosis factor-alpha (TNF-α-) induced apoptosis." (PMID 22969822, 2012). "Tumor necrosis factor-α (TNFα) is a pleiotropic cytokine originally recognized for its anti-tumor activity." (PMID 22632257, 2012). "The rationale is to administer sufficient doses of TNF to the tumour to induce acute inflammation, which frequently precedes the development of adaptive antitumour immunity." (PMID 23326670, 2012). "We used a multistage model of SCC to examine the involvement of elastase (ELA), myeloperoxidase (MPO), nitric oxide (NO), cytokines (IL-6, IL-10, IL-13, IL-17, TGF-β and TNF-α), and neutrophils and macrophages in tumour development." (PMID 23176085, 2012). "A second conclusion from these data are that the expressions of TERT, TRF2, TRF1, TIN2, and POT1 can be regulated by factors presumed to be at the tumor site, including mediators of stress (glucocorticoids) and inflammation (TNF-α)." (PMID 23342266, 2012). "TNF-α was found to induce p21 (waf1) protein in tumor cells, and it also induces p21 binding to CDK 2/4 and 6 complexes resulting in the inhibition of their activities." (PMID 23122182, 2012). "The capacity to control tumor growth by transferred Cl-IB-MECA-treated T cells was significantly affected in mice receiving the TNF-α mAb." (PMID 23028986, 2012).
tumor (continued). "These factors include proinflammatory cytokines such as TNF-α, IL-1β, and IL-6 and factors produced by tumour cells, each of which can be derived from the tumour itself and also from the host tissues." (PMID 22629149, 2012). "This would suggest that TNF-α shedding was confined to highly active regions of host-tumour interaction such as at the invading margins." (PMID 22792380, 2012). "Ectopic expression of MAP17 in tumor cells prevents TNF-induced G1 arrest by impairing p21waf1 induction." (PMID 22973555, 2012). "ASMq treated animals had reduced tumour volume compared to model and increased concentrations of TNF-α, IL-1β and IL-2 compared to untreated and to cyclophosphamide-treated animals." (PMID 22978453, 2012). "Inhibition of TNF expression has been focused on as one of the possible mechanisms to counteract tumor progression." (PMID 23243426, 2012). "In this setting, the ability of TNF to modulate the tumour vasculature has been exploited, allowing for greater accumulation of the chemotherapeutic drug within the tumour." (PMID 23326670, 2012). "Although initially thought to be a product only of macrophages, many malignant tumours are characterized by a constitutive production of TNF-α from the tumour microenvironment and its presence often associates with poor prognosis." (PMID 23905066, 2012). "TRAIL (tumor necrosis factor (TNF)-related apoptosis-inducing ligand) is a member of the TNF superfamily with the ability to induce apoptosis of tumor cells." (PMID 22788777, 2012). "TGF-β enhances tumour invasion and, with TNF-α, affects stromal cells, facilitates angiogenesis, and impairs NK cells, CD8+ T cells and macrophage activity against tumours." (PMID 23176085, 2012). "This is consistent with a study showing that suppression of CLIC family members, using an antisense approach, enhanced TNF-a-induced apoptosis in tumor cells." (PMID 22761775, 2012). "Injection of L19mTNFα conjugate induces a dramatic necrosis of established tumors as it allows concentrating therapeutically active doses of TNFα at the tumor level." (PMID 22849661, 2012). "We found that PDTC treatment significantly reduced the expression of TRAIL, IL-1β, TNFα, and MnSOD in the non-tumor bearing epidermis with a less appreciable decrease in tumors." (PMID 22761871, 2012). "A proinflammatory state is recognized by elevated infiltrating macrophages, T cells, tumor necrosis factor-alpha and C-reactive protein in the tumor microenvironment, and it is commonly present in patients with MetS." (PMID 22911869, 2012). "Previous reports show that TWEAK, which does not contain a death domain in its cytoplasmic tail, induces the apoptosis of tumor cell lines through the induction of TNFα secretion." (PMID 22438963, 2012). "TNF-α, in turn, is a well-known tumor promoter and has been identified as a master regulator of inflammation and a key player in the cytokine network between inflammation and cancer." (PMID 22860022, 2012). "It induces high expression of TNF-α through NF-κB activation and tumor-promoting activities in Bhas cells." (PMID 22860022, 2012). "It was discovered in a screen for monoclonal antibodies that reversed the macrophage-resistant phenotype of tumor cells, making them more sensitive to killing by macrophage-elaborated tumor necrosis factor-alpha (TNF-α)." (PMID 24213471, 2012). "It increased the production of Th1 and Th2 cytokines within the intestine and tumor, including TNF, IFN-γ, as well as nitric oxide that have been reported to sensitize tumors to chemotherapy." (PMID 23231648, 2012). "The net effect of the changes in gene expression would thus be to promote the ability of TNF to augment NF-κB-dependent cell survival, while blocking its ability to induce tumor cell death via activation of TNFR1." (PMID 22225778, 2012).
tumor (continued). "The proinflammatory cytokine TNF-α has been shown to play a promoting role for tumor development, and activation of NF-κB, a downstream signaling transducer of TNF-α, has long been implicated in the development of HBV-associated HCC." (PMID 22848663, 2012). "IGROV1-Luc cells secrete TNF-α and knockdown of TNF-α expression by transfection of IGROV1-Luc cells with anti-TNF-α shRNA was reported previously to inhibit tumour growth." (PMID 22792380, 2012). "Taken together our in vivo evidence demonstrates the critical role of TNF-α in the Cl-IB-MECA-treated CD8+ T cell-induced immune response within the tumor lesion." (PMID 23028986, 2012). "TNF-α is indeed critical for the anti-tumor T cell immunity in mice and is required for the optimal functional T cell response to tumors." (PMID 23028986, 2012). "In a complex series of events, FAP+ cell depletion results in damage to the vasculature and hypoxic tumor necrosis which involves the cytokines interferon gamma (IFNγ) and TNFα." (PMID 24213314, 2012). "RGD and NRG peptide-targeted TNF-α treatment decreased tumor growth with smaller doses than free TNF-α." (PMID 23316341, 2012). "Tumour angiogenesis is regulated by chemokines (monocyte chemo-attractant protein-1, IL-8) and growth factors (TNF, VEGF) produced by macrophages, neutrophils and other inflammatory cells." (PMID 23905066, 2012). "Despite abundant evidence to suggest that TNF has a role which favours tumour progression, this cytokine was originally identified as a factor that strongly induced tumour necrosis, hence its name." (PMID 23326670, 2012). "CD16+ monocytes are reportedly the main monocyte population in the anti-cancer response and secrete high levels of TNF-α and IL-12 upon tumor cell interaction." (PMID 22973451, 2012). "The anti-cancer actions of TNF can be due to direct effects on tumour cells and/or indirect effects on host stroma, and many of these effects are potentiated by IFN-γ." (PMID 23905066, 2012). "We used TLR4 ligand LPS, TLR3 ligand polyI:C and the Jonuleit cytokine cocktail most commonly used in today’s DC-based tumor vaccines consisting of IL-1β, IL-6, TNF-α and PGE2 for the generation of immunogenic DC." (PMID 23185370, 2012). "It has been shown that HDL reduces free TNF-α resulting in reduced tissue damage, reduced infiltration of macrophages and neutrophils, and potential attenuated tumor formation." (PMID 23092358, 2012). "In SCC, TNF mRNA expression was also significantly elevated in the tumor margin compared to normal skin (176.2±89.4, p<0.05)." (PMID 22808251, 2012). "We also saw clear examples of the complexity of tumour biology, where TNF-α/IL-6 pathways were activated by DMXAA in both A375 cells and stromal cells." (PMID 22415295, 2012). "Cytokines such as interleukin (IL)-6, IL-17A, IL-21 and tumor necrosis factor (TNF)-α contribute to the formation of a tumor-supportive microenvironment, while interferon (IFN)-γ is supposed to exert tumor-suppressive functions." (PMID 23109839, 2012). "Although TNFα was first identified for its ability to induce rapid hemorrhagic necrosis of experimental cancers, TNFα is now known to be produced in cancer cells as an endogenous tumor promoter." (PMID 22675434, 2012). "Tumor Necrosis Factor-α (TNF-α) is a pro-inflammatory cytokine produced and secreted primarily by macrophages and monocytes in response to a bacterial challenge or tumor burden." (PMID 22479555, 2012). "Like ways, AKT activation has been described as responsible for TNF resistance in some tumor cell lines." (PMID 22973555, 2012). "These immune cells release pro-inflammatory molecules, such as TNF-α, IL-6, and IL-1α, which activate signaling pathways and promote tumor growth." (PMID 23272179, 2012). "Different mathematical models have been previously established for TNFα/NFκB signaling in the context of tumor cells." (PMID 23293603, 2012).
tumor (continued). "True to its name, TNF is cytotoxic to tumour cells under certain conditions; however, it also fuels tumour-promoting inflammation and angiogenesis." (PMID 23326670, 2012). "Expressions of interleukin-6 (IL-6), IL-8, interferon (IFN)-gamma, and tumor necrosis factor (TNF)-alpha mRNAs were also detected in tumor tissue, while IL-1-alpha, IL-1-beta, IL-2, IL-4, and COX-2 mRNAs were not." (PMID 22844297, 2012). "In our study, we used IFNγ and TNFα stimulating human MSCs from bone marrow to imitate the tumor inflammatory microenvironment, and then co-cultured with different HCC cells." (PMID 22952657, 2012). "The expressions of numerous cytokines that are growth factors for tumor cells such as interleukin 1β (IL-1β); tumor necrosis factor (TNF); epidermal growth factor (EGF) and IL-6 are also regulated by NF-κB." (PMID 22873280, 2012). "For this purpose, mice were injected with 10 μg/mouse of mAb anti-TNF-α or IgG control (mouse IgG) every day starting from day 10 after tumor cell implantation." (PMID 23028986, 2012). "Using an experimental model of tumor necrosis factor-alpha (TNF-α)-mediated inflammation, we characterized inflammatory gene expression in immunopurified tumor-associated endothelial cells." (PMID 23056240, 2012). "TNF exhibits both tumour-promoting and tumour-inhibitory properties, depending on the experimental context within which the conclusions are made." (PMID 23326670, 2012). "Tumor growth in mice treated with anti-TNF-α mAb (dashed lines) was compared with that measured in mice treated with the IgG control (continuous lines)." (PMID 23028986, 2012). "For this protein to be excreted in levels high enough to act as an antitumour agent, ways must be developed which would either allow increased TNF-α production at the tumour site or utilized the synergistic effect of interleukin-2 and TNF-α." (PMID 22737166, 2012). "TNF is predominantly produced by macrophages, T cells and natural killer (NK) cells, but nonimmune cells such as fibroblasts, smooth muscle cells, and tumour cells have also been reported to secrete low amounts of the cytokine." (PMID 23326670, 2012). "Innate immune cells such as macrophages and dendritic cells cohabit the tumor stroma and are thought to play important roles in tumor progression via secretion of pro-inflammatory cytokines such as IL-1, IL-6, TNF-α and others." (PMID 22529912, 2012). "The proinflammatory cytokine tumour necrosis factor alpha (TNF-α) plays a unique role in the tumour environment where it permits cellular communication and is capable of promoting both growth and necrosis." (PMID 22737166, 2012). "TNF-α also activates nuclear factor-κb (NF-κb), a transcription factor, which stimulates the proliferation of tumour cells and regulates antiapoptotic genes, and thus can protect the cancerous cells from the apoptotic cascade induced by TNF-α." (PMID 22737166, 2012). "More recently, it has been demonstrated that VE-cadherin is a target of TNF-α, leading to the alteration of vascular integrity and tumour viability." (PMID 22719951, 2012). "Inhibition of NF-κB activation and sustained JNK activation promote the TNF alpha mediated cell apoptotic and suppress the tumour progression." (PMID 22676414, 2012). "Secretion of IL-12 and TNF-α was induced by adding rHsp70 or rHsp70C′-PSA to the irradiated tumor cell/DC cultures." (PMID 23112956, 2012). "Of note, versican also binds to TLR-2 and acts as an agonist for the receptor to activate tumor-infiltrating myeloid cells by increasing production of cytokines, like TNF-α, to promote tumor metastasis." (PMID 24213471, 2012). "When chronically produced in the tumor microenvironment, TNF-α is a major mediator of stromal inflammation." (PMID 23056240, 2012). "TNF constitutes a highly potent antineoplastic drug, which however so far cannot be applied to patients with primary and secondary tumors of the liver due to its profound hepatotoxicity." (PMID 23272249, 2012).